TNF (tumor necrosis factor)
Diseases named in the same sentence as TNF in open-access papers (continued):
Sharing a sentence is not in itself a finding about the gene and the disease.
tumor (continued). "The levels of IFNγ, TNFα, IL-5, and IL-6 were significantly higher in the mice with tumors than in the tumor-free mice." (PMID 35223517, 2022). "For instance, activation of TNFR1 by TNFα can lead to tumor cell death but under a different set of conditions it can contribute to cancer inflammation and enhance tumor progression." (PMID 35663982, 2022). "In 1975, Carswell and his colleagues initially identified TNF as a cytokine that leads to the necrosis of tumor tissue." (PMID 35741080, 2022). "In a mice model with CRC, pasteurised A. muciniphila and Amuc_1100 increased the activation of CTLs in the MLN and the proportion of tumor necrosis factor-alpha (TNF-α)+ CTLs to promote the apoptosis of tumor cells." (PMID 36253412, 2022). "In vivo, tramadol administration decreased the expression of inflammatory cytokines such as IL-6 and tumor necrosis factor-α (TNF- α), which are involved in tumor growth and invasion, and maintained NK cell activity, unlike morphine." (PMID 35223475, 2022). "It has become increasingly clear that the tumor-associated neutrophil (TAN) N1 type releases immunostimulatory or pro-inflammatory cytokines, comprising CXCL10, CCL3, and tumor necrosis factor (TNF)-α, which promote CD8+ T cell recruitment and activation." (PMID 36613779, 2022). "The RANTES tumor levels correlated significantly with those of PD-L1, TNF-α, TGF-β, VEGF-A, and VEGF-C." (PMID 35208526, 2022). "Tumor necrosis factor α (TNF-α) is a pro-inflammatory cytokine produced and secreted primarily by macrophages and monocytes in response to bacterial challenges or tumor burdens." (PMID 35209003, 2022). "Depletion of fibroblast activation protein-positive (FAP+) stroma cells enables immunological control of tumor growth by IFNγ and TNFα." (PMID 36230914, 2022). "TNF-α is an inflammatory mediator produced by leukocytes, tumor cells, and other cells in the tumor microenvironment." (PMID 36185234, 2022). "TNFα is considered to be one of the most important inflammatory cytokines among the numerous cytokines secreted in the tumor milieu." (PMID 36290384, 2022). "For one thing, TNF-α can exert anti-tumor effects by inducing apoptosis, participating in the body’s immune response, and inducing programmed cell necrosis, and has been used clinically as an anti-tumor agent." (PMID 35574296, 2022). "Recently, a phase I clinical trial of DNX-2401 treating patients with recurrent GBM suggested increased numbers of macrophages and proinflammatory factors, including IL-6 and TNF-α, in posttreatment tumor specimens." (PMID 36013403, 2022). "The ways in which TAMs kill tumor cells seem similar to what is observed in infections, mainly through the production of reactive oxygen species (ROS), NO and TNFα." (PMID 35884605, 2022). "Previous research suggests that newly tumor-infiltrated naive M0 macrophages play anti-tumorigenic activities via release of TNF-α secretion." (PMID 35965524, 2022). "The levels of pro-inflammatory M1 marker CD86 and tumor-killing cytokine TNF-α were significantly up-regulated by PA-MSHA as well." (PMID 36344505, 2022). "Alterations in the tumor environment were further supported by the enrichment of inflammatory-related signaling pathways including tumor necrosis factor (TNF), Toll-like receptor, and interleukin (IL)-17, which are overexpressed in CSCs." (PMID 35631492, 2022). "Tumors had little effect on liver cytokines with the exception of TNF-α, which was lower in the livers of the Tumor group compared with the Reference group (p < 0.05)." (PMID 36428795, 2022). "CD4+ T cells have been shown to initiate a strong antitumor response in tumors by enhancing the clonal expansion of cytotoxic T lymphocytes as well as directly through the secretion of TNF-α and other tumor-suppressive factors." (PMID 35565302, 2022). "Tumor necrosis factor alpha (TNF-α) is an important proinflammatory cytokine and the only known cytokine that can directly kill tumor cells." (PMID 36593850, 2022).
tumor (continued). "As a major proinflammatory cytokine, TNF acts as an endogenous tumor promoter, bridging inflammation and carcinogenesis." (PMID 36230879, 2022). "Then, tumor-specific cytotoxic T lymphocytes are activated, accompanied by the release of immune-promoting cytokines such as IFN-γ and TNF-α to kill tumor cells." (PMID 35541893, 2022). "TNF-α can not only kill tumor cells directly but also induce immature DC to differentiate into mature DC." (PMID 36209263, 2022). "Nonetheless, peripheral blood of tumor-burdened mice that were treated with this type of NP contained higher frequencies of CD8+TNF-α+IFN-γ+ T cells." (PMID 35693776, 2022). "Tumor necrosis factor alpha (TNFα) is another inflammatory cytokine that can promote tumor progression, survival, and metastasis." (PMID 35216045, 2022). "The results of KEGG analysis indicated that the PI3K-Akt signaling pathway, MAPK signaling pathway, proteoglycans in cancer, IL-17 signaling pathway, cellular senescence, and TNF signaling pathway were mainly involved in the regulation of tumor cells." (PMID 36003525, 2022). "Although TNF members was initially found to mediate anti-tumor effects, recent studies have shown that they also promoted tumor progression." (PMID 35000592, 2022). "On the other hand, as an endogenous pyrogen, TNF-α is able to mediate fever, apoptotic cell death, sepsis (through IL-1 and IL-6 production), cachexia, tumor regression, as well as carbohydrate metabolism and adipogenesis inhibition." (PMID 35406450, 2022). "We have previously shown that both IFN-γ and TNF-α are important in the induction of differentiation of tumor cells as well as healthy stem cells." (PMID 36359827, 2022). "To investigate cytokine secretion profiles of 28z/IL-7-CAR-T cells against Raji cells, we measured the IFNγ and TNFα response after co-culturing with tumor cells using flow cytometry." (PMID 35869100, 2022). "Reduction in tumor necrosis factor production is also an important mechanism ofanticancer action, since the presence of necrosis stimulates tumor phosphorescencemediators, favoring angiogenesis and tumor metastasis." (PMID 36542014, 2022). "Mature dendritic cells can initiate T cells in the background of MHC I and II molecules cells, triggering CTL killing of tumor cells through TNF-TNFR signaling, perforin/granzyme pathway." (PMID 36176401, 2022). "Previous literature indicates that inflammatory factors, such as TNF-α, can promote tumor growth and poor prognosis of HCC." (PMID 36578460, 2022). "In general, IL-1β and TNF-α are well-known cytokines acting as representative mediators of tumor cytostasis." (PMID 35996139, 2022). "TNF-α and IL-6 are critical tumor promotors during tumorigenesis and colonic carcinogenesis in humans and mice." (PMID 35865942, 2022). "Both IL-6 and TNF-α, which have dual roles in immune response to tumor, were also elevated with the combination treatment." (PMID 36551577, 2022). "Estrogen also appears to weigh the tumour immune balance towards tumour-promoting cytokines (IL-6, IL-4, TNF and IL-17A), M2 (pro-tumour) macrophage polarisation and diminished functional capacities of anti-tumour NK and CD8+ T cells." (PMID 36347875, 2022). "IL-8, macrophage movement inhibitory factor, and fibrinolytic enzyme activator inhibitor 1 secreted by metastatic lung cancer cells can activate astrocytes that produce growth factors (IL-6, IL-1, and TNF-α), encouraging tumor growth." (PMID 35251014, 2022). "Consistently, TNFα upregulated Runx2, a tumor-promoting transcription factor, and Snail, a regulator of EMT, in SW1353 CS cells." (PMID 35804814, 2022). "CML-MSCs enhance immunosuppressive MDSCs production and aggregation, promoting tumor progression via upregulating immunomodulatory arginase-1 (Arg-1), IL-6, IL-1β, COX-2, and TNF-α in MDSCs and inhibiting anti-tumor immunity." (PMID 35842634, 2022).
tumor (continued). "In what follows we use a simplified notation where Tα(t) denotes the average concentration of TNF-α in the tumor at time t, and Tα,con(t) denotes Tα(t) in the control case (no drugs)." (PMID 36355837, 2022). "Cytotoxic CD8+ T cells recognize HER2 antigen peptides presented by MHC class I molecules, and secrete IFN- γ and TNF-α, thereby killing tumour cells." (PMID 35804943, 2022). "These cytokines (IL-1, IL-6, TNF, IL-17, etc.)have been proved to promote tumor cell proliferation, angiogenesis and metastasis." (PMID 36104733, 2022). "Ligand TNF and its receptor TNFRSF1B were found to act as major signaling from CD4+ T cells to CD8+ T2/T3 cells, and the ability of the TNF–TNFRSF1B pair to kill tumor cells in vitro has been reported before." (PMID 35812372, 2022). "PADI4 upregulates the expression levels of KRT14, CXCR2 and TNF-α, which are related to cell proliferation, cell migration, tumour angiogenesis, and tumour immune microenvironment." (PMID 35045833, 2022). "TNF-alpha stimulates tumor cell death through its antiangiogenic effects that destroy blood vessels supplying to the tumor." (PMID 35455349, 2022). "Candida produces nitrosamines that alter cell proliferation and secretes cytokines such as tumor necrosis factor-alpha (TNF-α) and interleukin (IL) 18 (IL-18) that modulate the immune response and promote tumor cell adhesion to epithelial cells." (PMID 35642013, 2022). "Pro-inflammatory cytokine production including tumor necrosis factor α (TNFα), IFNγ, and IL-2 were significantly elevated in tumor-infiltrating CD8 + T cells from Salmonella + Alb-IL2 treated mice compared to mice treated with Salmonella or Alb-IL2 alone." (PMID 35962391, 2022). "The role of TNF in tumorigenesis, tumor growth and metastasis has been demonstrated in vitro and in various mouse tumor models, including colon cancer and skin cancer." (PMID 36289890, 2022). "The surface of dying tumor cells after conjugation with CpG‐NPs displayed great promotion in DCs maturation and cytokines (IL‐12 and TNF‐α) secretion compared with a physical mixture of free CpG and dying tumor cells." (PMID 35652198, 2022). "Cytokines regulated by NF-κB and STAT3 can either be tumor-inducing (TNF, IL-23, IL-6) or tumor-inhibiting (IFNα, IFNγ, TRAIL)." (PMID 35327456, 2022). "Concerning NK cells, adenosine has been reported to inhibit their cytotoxic activity against tumor cells and their production of TNF-α, IFN-α, and GM-CSF." (PMID 36713558, 2022). "The role of TNF in the pathogenesis of malignancy is mixed, with both pro-tumor and anti-tumor effects." (PMID 36081549, 2022). "Next, by gene set enrichment analysis, we found that the inflammatory cytokine TNF-α signaling pathway and the epithelial–mesenchymal transition pathway, which promotes tumor invasion and metastasis, were both upregulated in the VTE group." (PMID 35326647, 2022). "The TNF-α was scattered randomly and diffusely within the tumor cells and only in those co-cultured with MCs sensitized with HER2/neu Abs." (PMID 35740607, 2022). "Our ECM-depletion approach to improve tumor perfusion using TNFα-CSG is also consistent with other ECM-reducing strategies to enhance perfusion and increase access to solid tumors." (PMID 35273916, 2022). "High-dose radiation therapy of HNSCCs results in the significant induction of TNF-alpha, which can be measured in serum, and the complete tumor response to radiation has been strongly correlated with the induction of TNF-alpha levels in serum." (PMID 35740551, 2022). "NK cells express a variety of cytokine receptors related to chemotaxis and activation and can be recruited to the tumor microenvironment to kill tumor cells by releasing perforin, granzyme, and tumor necrosis factor-α and expressing FasL." (PMID 35720360, 2022).
tumor (continued). "MDSCs release IL-10 to downregulate IL-12 secretion by macrophages while macrophages in turn induce MDSCs to increase IL-10 which decreases IL-6 and TNF-α in macrophages and therefore skewing the immunity towards tumor promoting type 2 response." (PMID 35183252, 2022). "Stimulated CD4+ T helper 1 cells secrete the effector cytokines interferon-gamma (IFN-γ) and tumor necrosis factor alpha (TNF), which induce senescence in tumor cells." (PMID 35563820, 2022). "TNFα is a cytokine that mainly participates in inflammation and immune response, while in tumors, it’s reported that TNFα-NF-κB signaling plays a crucial role in promoting tumor cell migration and invasion." (PMID 36338696, 2022). "TNF administration induces short-duration vascular disruption in many cancers, transiently enhancing tumor permeability and ultimately reducing blood flow." (PMID 36551505, 2022). "The contributions of known pro-inflammatory cytokines such as TNF-α to anti-tumor immunity remain controversial." (PMID 35909944, 2022). "In a recent study, short-term pharmacological inhibition of ADAM17 via delivery of recombinant prodomain (PD) impairs TNF-induced necroptosis in tumor endothelial cells and subsequently blocks metastasis." (PMID 36361505, 2022). "One of the cytokines secreted is TNFα, which in turn activates NF-κB, which promotes tumor metastasis and invasiveness." (PMID 36009267, 2022). "SAA3 protein produced in response to S100A8 in the lungs also attracts and recruits circulating tumor cells to the niche and stimulates the production of inflammatory cytokines, such as TNFα, which promote tumor growth." (PMID 36497411, 2022). "Some tumor-associated pathways, such as the angiogenesis, EMT, hypoxia, glycolysis and TNFα-NFκB pathways, were up-regulated in the CAF-high group." (PMID 36568368, 2022). "To demonstrate proof‐of‐efficacy of TPA‐mediated cytokine therapy in a PDX model, we chose to deliver a TNFα transgene, since this cytokine can induce direct tumour cell death." (PMID 35758207, 2022). "Inflammatory cytokines, such as interleukin-1, interleukin-6, and tumor necrosis factor α, not only promote angiogenesis, tumor growth but also impair cell-mediated immune response." (PMID 35797279, 2022). "Comparing the tumorigenic potential of Winnie-ApcMin/+-TNF-KO mice with the already published Winnie-ApcMin/+ model, a different modulation for the incidence, multiplicity, and tumor grading of the tumoral lesions was reported." (PMID 36499472, 2022). "TNF in the tumor microenvironment can induce cancer malignancy through genetic damage or directly affect the EMT." (PMID 36613819, 2022). "Tumor-infiltrated M1 macrophages secrete anti-tumor factors such as iNOS and TNFα, which induce apoptosis in cancer cells, thereby contributing to improved patient survival." (PMID 35205790, 2022). "In pancreatic tumors, the secretion of TNF-α and IL-1β by tumor cells promotes CAFs activation and their secretion of TSLP, which favor the generation of DCs with Th2-polarizing capabilities, associated with reduced patient survival." (PMID 36338519, 2022). "Under these conditions, it is in the “interest” of TNFα—as a pro-tumor factor—to down-regulate the expression of protective sTNFR1, in that way, leading to higher levels of pro-metastatic chemokines at the TME." (PMID 35884574, 2022). "Pathway analysis indicated that the DEGs were involved in multiple tumor-associated pathways, such as PI3K-Akt signaling, MAPK signaling, eGMP-PKG signaling, TNF signaling pathways, etc.." (PMID 35844795, 2022). "KEGG pathway analysis displayed that these DENRGs were involved in multiple tumor-related signaling pathway including necroptosis, apoptosis, TNF signaling pathway, IL-17 signaling pathway, and Toll-like receptor signaling pathway." (PMID 35918354, 2022).
tumor (continued). "For instance, CD1dhiCD5+ Bregs produce IL-10 and downregulate the production of NO, TNFα, and the expression of activation markers by monocytes and macrophages limiting their anti-tumour activity." (PMID 35350071, 2022). "Mature cDCs and pDCs (monocyte-derived) can secrete cytokines (IL-1β, IL-12, IL-18, IFN-γ, and TNF-α) that activate Vγ9Vδ2+ T cells, enhancing their proliferation and cytotoxic function (IL-18-mediated cytotoxicity against tumor cells)." (PMID 35880177, 2022). "In a co-culture with tumor cells, TANs from IFN-β-deficient mice showed significantly lower cytotoxicity and TNF-α expression in comparison with TANs from wild-type mice." (PMID 36555469, 2022). "We used TPA to target the delivery of cytokine‐encoding transgenes for interleukin‐12 (IL12), and novel isoforms of IL15 and tumour necrosis factor alpha (TNFα) for tumour immunotherapy." (PMID 35758207, 2022). "Then, we showed that CBX7 downregulated ETS1 to inactivate the tumor necrosis factor (TNF) signaling pathway, which inhibited tumor proliferation and enhanced the sensitivity of ccRCC cells to tyrosine kinase inhibitors (TKIs)." (PMID 35342353, 2022). "Intracellular TNF-α expression in DCs was also assessed to show the cytokines that regulate the effector functions of DCs for tumor immunity." (PMID 35444547, 2022). "There has been evidence that TNFα increases proliferation and invasion of cancer cells, thereby promoting tumor progression and cancer metastasis." (PMID 36290384, 2022). "TNF-α is a known critical player in tumor signaling pathways and immune cell manipulation within the TME and is mainly produced by activated macrophages, T lymphocytes, and natural killer (NK) cells." (PMID 35327456, 2022). "The shift in macrophage polarity towards the inflammatory M1 type can be induced by cytokines associated with inflammation and removal of tumor cells and pathogens, e.g., IFN-γ, LPS, TNFα, and GM-CSF." (PMID 35418973, 2022). "As in prior experiments, Myc-CaP allograft volumes were measured using HFUS imaging and tumor-bearing mice were pretreated with sTNFR2-Fc (or vehicle) to block TNF signaling, and then castrated." (PMID 36551505, 2022). "Among them, the ECM−receptor interaction pathways, TNF signaling pathway, pathways associated with cancer, PI3K-AKT signaling pathway, and other tumor-related pathways were significantly enriched." (PMID 36213837, 2022). "Co-culture with macrophages treated with tumor exo-NAC or exo-miR-155-5p increased TNF-α, IFN-ɣ, and IL-2 levels in T cells." (PMID 35086548, 2022). "For example, the rodent form of IgE MOv18 reduced lung metastases in a syngeneic rat tumor model expressing human FRα which was attributed to TNFα, IL-10, and MCP-1 released by MOv18-triggered monocytes." (PMID 35433433, 2022). "First, MCs form TnT with the cancer cells and appear to transfer TNF-α specifically to the tumor cell." (PMID 35740607, 2022). "In Lewis lung carcinoma and fibrosarcoma transplantation mouse models, tumor cell-derived TNFα prompts neutrophils to express the hepatocyte growth factor receptor (HGFR; also known as MET)." (PMID 36514901, 2022). "Tumor-infiltrating M1-type macrophages (anti-tumorigenesis) secrete proinflammatory cytokines (e.g., IL-1β and TNF-α), whereas tumor-infiltrating M2-type macrophages (pro-tumorigenesis) secrete anti-inflammatory cytokines (e.g., IL-6 and IL-10)." (PMID 36246355, 2022). "Among the 79 transcription factors, IRF1 was not only at the core in the gene interaction network but also enriched in the famous tumor pathway TNF, as detected by KEGG enrichment analysis." (PMID 36035205, 2022).